COL20A1 (collagen type XX alpha 1 chain)
Description:
Probable collagen protein.
Synonyms: KIAA1510
Tractability: Antibody: UniProt places it where antibodies can reach, with high confidence; its Gene Ontology location is reachable by antibodies, with high confidence; UniProt predicts a signal peptide or a membrane-spanning region.
Gene: Protein-coding gene on chromosome 20 (63,293,186 to 63,334,851, forward strand). Ensembl gene ENSG00000101203.
Subcellular location: Secreted, extracellular space
Subcellular location (Human Protein Atlas): Golgi apparatus; Vesicles; Predicted to be secreted
Pathways (Reactome):
Extracellular matrix organization: Collagen biosynthesis and modifying enzymes; Collagen chain trimerization
Gene Ontology:
Cellular component: collagen type XX trimer; endoplasmic reticulum lumen; extracellular matrix; extracellular region
Genetic constraint (gnomAD): Loss-of-function variants: 161 observed, 129.27 expected, observed/expected ratio (o/e) 1.25, 90% interval 1.1 to 1.42. The synonymous counts are far from expectation, so gnomAD's model fits this gene poorly and the ratio says little. Missense variants: 1,867 observed, 1,552.9 expected, observed/expected ratio (o/e) 1.2, 90% interval 1.16 to 1.25. Synonymous variants: 861 observed, 676.19 expected, observed/expected ratio (o/e) 1.27, 90% interval 1.2 to 1.35.
Homologues: Orthologues: chimpanzee COL20A1 (98% identical), macaque COL20A1 (93% identical), mouse Col20a1 (73% identical). Paralogues in human: COL5A1 (19% identical), COL11A1 (19% identical), COL11A2 (19% identical), COL1A1 (18% identical), COL2A1 (18% identical), COL5A3 (17% identical), COL3A1 (17% identical), COL5A2 (17% identical), COL4A4 (16% identical), COL4A1 (16% identical), COL1A2 (16% identical), COL4A2 (16% identical), and 25 more.
Diseases named in the same sentence as COL20A1 in open-access papers:
COL20A1 is named in the same sentence as 15 diseases in open-access papers, as found by Europe PMC text mining. Sharing a sentence is not in itself a finding about the gene and the disease. The quoted sentences say what the papers report.
diabetic kidney disease (4 papers, 2023 to 2025). Progressive kidney disorder caused by vascular damage to the glomerular capillaries, in patients with diabetes mellitus. "The COL20A1 gene has been associated with a variety of conditions, including pulmonary fibrosis, palmoplantar keratoderma, diabetic kidney disease, and several cancers." (PMID 40700040, 2025). "While PKD1 is involved in the maintenance of renal epithelial differentiation and organization, single nucleotide polymorphisms in the COL20A1 locus are associated with diabetic kidney disease." (PMID 38093359, 2023). "Genome Wide Association Studies (GWAS) identified a series of single nucleotide polymorphisms in COL20A1 in association with diabetic kidney disease." (PMID 38093359, 2023). "A genome-wide meta-analysis linked the COL20A1 gene to diabetic kidney disease." (PMID 37630778, 2023). "In recent years, researchers have conducted more and more large‐scale GWAS and Mendelian randomization analysis to explore the genetic variation related to diabetes nephropathy, including UMOD, COL4A3, COL20A1, TENM2, SLC47A1, and so forth." (PMID 40931579, 2025).
pulmonary fibrosis (2 papers, 2025). Chronic progressive interstitial lung disorder characterized by the replacement of the lung tissue by connective tissue, leading to progressive dyspnea, respiratory failure, or right heart failure. "As the Collagen-I plays a crucial role in fibrogenesis and the pulmonary fibrosis is characterized by its accumulation, the reduction in Collagen-I deposition caused by knocking out the COL20A1, COL27A1, and WNT11 may indicate a potential direction for pulmonary fibrosis treatment." (PMID 40034336, 2025). "By applying the loss-of-function experiment, the COL20A1, COL27A1, and WNT11 were confirmed as key profibrotic regulators of EMT and development of pulmonary fibrosis." (PMID 40034336, 2025). "Interestingly, enhanced expression of the collagen protein coding gene-COL20A1 was detected in experimental models of pulmonary fibrosis." (PMID 40034336, 2025). "To further consolidate the findings of our study, we analyzed the expression levels of COL20A1, COL27A1, and WNT11 in patients with pulmonary fibrosis." (PMID 40034336, 2025). "Our results demonstrate that the COL20A1, COL27A1, and WNT11 are key profibrotic regulators of IPF, and the knockout of these genes attenuated the TGF-β1-induced EMT and pulmonary fibrosis in vitro." (PMID 40034336, 2025). "Altogether, all of our findings demonstrate that the COL20A1, COL27A1, and WNT11 serve as key profibrotic regulators and may play a crucial role in regulating the TGF-β1-induced EMT and the pathogenesis of pulmonary fibrosis." (PMID 40034336, 2025).
astrocytoma (1 paper, 2025). "For example, COL20A1 and SPOCK1 were elevated in TCs for grade II and 3 astrocytoma samples respectively." (PMID 41366031, 2025).
glioblastoma (1 paper, 2020). The most malignant astrocytic tumor (WHO grade IV). "COL20A1 occurs upregulated in glioblastoma and prostate cancer in response to pro-survival and inflammatory-related proliferation." (PMID 32986378, 2020).
glioma (1 paper, 2022). A benign or malignant brain and spinal cord tumor that arises from glial cells (astrocytes, oligodendrocytes, ependymal cells). "In a separate study, using biopsy-derived glioma cell models, a downregulation of COL20A1 RNA was observed after treatment with histone deacetylase inhibitors." (PMID 35456962, 2022). "Based on cDNA microarrays, COL20A1 was elevated in so-called brain-tumor initiating cells versus regular glioma cell lines and normal brain astrocytes." (PMID 35456962, 2022).
neuronal tumor (1 paper, 2023). Neuronal brain tumors are an uncommon group of central nervous system tumors that arise from cells with neuronal differentiation. "For example, COL20A1 is highly expressed in neural systems and was also only expressed in neuronal tumors." (PMID 37414817, 2023).
cancer (5 papers, 2013 to 2025). A tumor composed of atypical neoplastic, often pleomorphic cells that invade other tissues. "Similarly, testis-restricted targets such as SPA17, TEX14, LAMA1, SMOC1, TNFAIP6, GPC2, and COL20A1 may also be leveraged for their cancer-specificity." (PMID 38702309, 2024). "However, unlike COL20A1, COL17A1 is found in subsets of tumors in a number of cancers." (PMID 37414817, 2023).
tumor (4 papers, 2020 to 2025). "The COL20A1 enhancer was also identified in the primary tumor specimens, and its accessibility was restricted to a single cluster of tumor cells in three out of four primary samples profiled by scATAC-seq." (PMID 37244935, 2023). "In detail, tumor cells upregulated COL20A1, COL28A1 and TGFB1 expression to recruit more myofibroblasts in TTs compared with in PTs." (PMID 35361264, 2022). "In contrast, the down-regulation of SPON2 and COL20A1 would exert a tumor-restraining activity." (PMID 32911675, 2020). "While matrisome transcripts like ITGA5 and LGALS3 were enriched in TCs and infiltrating stromal cells residing around necrotic regions, the hypoxic tumor regions revealed enhanced expression of IGFBP2 and COL20A1." (PMID 41366031, 2025).
COL20A1 also shares sentences with these, for which no sentence is quoted: breast carcinoma (2 papers); infection (2); atherosclerosis (1); diabetes mellitus (1); ischemic stroke (1); Palmoplantar keratoderma (1); prostate carcinoma (1).